BMI1 (BMI1 proto-oncogene, polycomb ring finger)
Diseases named in the same sentence as BMI1 in open-access papers (continued):
Sharing a sentence is not in itself a finding about the gene and the disease.
tumor (continued). "Depletion of BMI1+ CSCs may thereby be an efficient strategy for improving anti-PD-1 therapy efficacy and preventing tumor recurrence." (PMID 36810098, 2023). "Accordingly, we found a higher expression of the stem cell marker CD133 and of the self-renewal marker Bmi1 in tumor xenografts sections derived from CTCDOs, while the differentiation marker CK20 was expressed at lower levels as compared to XDOs-derived xenografts." (PMID 35260172, 2022). "The expression of Bmi-1 is closely related to tumor migration and invasion." (PMID 35897796, 2022). "The tumor suppressor SIK1 was identified as the direct target gene of BMI1 in OS cells." (PMID 35346195, 2022). "Interestingly, the inhibition of Bmi-1 activates immune responses in tumor cells and recruits CD8+ T cells." (PMID 35897796, 2022). "It was reported that BMI1 or ARHI (DIRAS3) could induce autophagy-mediated necroptosis and necroptosis could augment tumor-associated macrophages M1 polarization and autophagy through other pathways." (PMID 36357839, 2022). "Therefore, the role of BMI1 in regulating OS tumor cells remains controversial and requires further investigation." (PMID 35346195, 2022). "At present, there are few reports on the effect of Bmi-1 on the tumor microenvironment." (PMID 35897796, 2022). "Co-expression of USP22 and BMI1 can accelerate tumor proliferation, stemness, and drug resistance." (PMID 35935969, 2022). "The expression of Bmi-1 can also affect the tumor microenvironment (TME)." (PMID 35897796, 2022). "In addition, our data revealed that SOX2 and BMI1 expression levels in tumor samples were also higher than those in normal tissues." (PMID 36411870, 2022). "Inhibition of BMI1 would accelerate tumor cell death in vivo by clearing senescent cells." (PMID 35566032, 2022). "Enrichment analysis of BMI1 downstream targets showed that BMI1 might be involved in tumor immunotherapy." (PMID 36199791, 2022). "The expression of stemness‐related markers, including CD133, ALDH1A1, Bmi1, Oct3/4 and Nanog, was inhibited dramatically, which might be the main reason for the downregulation of cell proliferation and tumour growth capacities." (PMID 34997691, 2022). "In conclusion, our data confirm PTC:PD anti-tumor effects in vivo and provide preclinical evidence that BMI1 and MAPK/ERK could be targeted in patients with BMI1High;CHD7Low MB." (PMID 35213723, 2022). "However, stromal BMI-1 expression is reflecting EMT involvement in tumor progression and the interrelationship between the two cellular components, which result in BMI-1 synthesis as a stromal-dependent mechanism." (PMID 34199929, 2021). "Tumor-associated epithelial ATII-like clusters and the epithelial cluster specific to mutant-KRAS ADCs, are positive for the oncogene BMI-1, and, according to our hypothesis, responsive to PTC596 in vivo treatment." (PMID 33854168, 2021). "Thus, the suppression of Bmi-1 expression is related to the functional inhibition of CSCs, which form malignant tumor cells." (PMID 34527741, 2021). "Therefore, a tight balance between proto‐oncogenes such as BMI1 and tumor surveillance mechanisms is essential for maintaining stem cell functions throughout life without developing tumors by disabling any cells susceptible to oncogenic transformation." (PMID 32840881, 2021). "Epithelial BMI-1 is progressively increased alongside the tumor grade and strong stromal BMI-1 may be correlated to microenvironment modulation, supporting the rapid growth pattern and the recognized poor prognosis in a subcategory of EOC cases." (PMID 34199929, 2021). "The increase in the ability of tumor cells to form spheres indicates that stem cells or mesenchymal level is enhanced, and the BMI1 gene plays an important role in maintaining self-renewal of tumor stem cells and has a pivotal role in chemotherapy sensitivity, tumor resistance, and tumor recurrence." (PMID 33927214, 2021).
tumor (continued). "Targeting BMI1 may eliminate CSCs by silencing PD-L1, and BMI1 inhibition can also attenuate tumor metastasis and recurrence by activating endogenous immunity." (PMID 34179009, 2021). "Interestingly, results of the real-time PCR also revealed increased expression of the Nanog, Oct4, Sox2, and Bmi1 mRNA transcripts (markers of the tumor-initiating cells) in the drug resistant cells." (PMID 34681918, 2021). "Considering the potential downregulation of miR-381 in BCa and its anti-tumor effects reported in other malignancies, we hypothesized that miR-381 inhibits malignant behaviors of BCa through the down-regulation of BMI1." (PMID 33407350, 2021). "Furthermore, we examined the protein levels of LSD1 and Bmi-1 in 14 fresh-frozen HNSCC tumor samples." (PMID 34689153, 2021). "Moreover, CCAT1 expression correlated with BMI1 mRNA and protein levels in both GC cells in vitro and in vivo in murine tumour models." (PMID 34321511, 2021). "Interestingly, USP22 has been reported to promote tumor cell stemness and development by stabilizing BMI1." (PMID 34753387, 2021). "Next, we interrogated two independent GBM single-cell RNAseq datasets, and confirmed that a significant number of tumour cells displayed a negative association between BMI1 and EFNA5." (PMID 31988455, 2020). "Furthermore, deficiency of DNACR obviously decreased the protein level of BMI1 in xenograft tumor tissues." (PMID 32099526, 2020). "Indeed, our results show that this axis promotes tumor cell survival and proliferation via p21CIP, since the restoration of BMI1 levels in SOX9 silenced cells, also modulated, in this case inhibited, the expression of this tumor suppressor." (PMID 31941916, 2020). "Importantly, Bmi1+ cells differentiated into a large chunk of the tumor of the Bmi1CreER;RosatdTomato mouse over time, consistent with previous studies." (PMID 32884573, 2020). "Based on these researches, we speculate that Bmi1+ tumor cells might mark CSCs and provide a novel therapeutic molecular target in ESCC." (PMID 32884573, 2020). "Analytical imaging of NODSCID mice with orthotopically implanted luciferase-tagged mGIC revealed that while 5/9 mice injected with control mGIC developed tumours and silencing of Bmi1 strongly suppressed tumour growth (0/9), concomitant silencing of EfnA5 and Bmi1 rescued tumour incidence (6/9)." (PMID 31988455, 2020). "Besides, inhibition of DANCR limited tumor growth by regulating miR-135a-5p and BMI1 expression in vivo." (PMID 32099526, 2020). "Interestingly, knockdown of BMI1 in human GIC (hGIC) significantly reduced tumour growth in a xenograft mouse model." (PMID 31988455, 2020). "We therefore hypothesized that miR-200c exerted its tumor suppressive function by reducing BMI1 expression in HCC." (PMID 33168810, 2020). "The fact that SOX9 modulation impacted on the expression of BMI1 in tumor cells in vitro and in vivo, suggested that BMI1 could constitute an effector of the pro-tumoral activity of SOX9." (PMID 31941916, 2020). "BMI1 is a proto-oncogene encoding a ring protein that is a major component of polycomb repressive complex 1, and PTEN encodes a phosphatase that acts as a tumor suppressor." (PMID 32899599, 2020). "Both YAP/TAZ and BMI-1 are regulators of self-renewal, differentiation, and tumor initiation of CSCs, indicating that glucocorticoids could induce ROR1-associated stemness phenotype in OC cells." (PMID 32989221, 2020). "Our previous studies have proved that Bmi1 is an important tumor stem cell marker of ESCC, so the targeted therapy of Bmi1+ cells may provide a possibility for the clinical treatment of ESCC." (PMID 32884573, 2020). "Furthermore, knockdown of BMI1 or USP15 inhibited the enhanced tumor growth by IL1R2 overexpression in vivo, and also inhibited the BTICs enrichment in the xenograft tumors." (PMID 31921558, 2020).
tumor (continued). "We found that the DEX-mediated increase of ROR1 levels correlated with the upregulation of RhoA GTPase, Hippo signaling effectors YAP/TAZ as well as BMI-1 expression, resulting in stemness phenotype and differentiation of OC tumor cells, including platinum-resistant samples." (PMID 32989221, 2020). "They suggested that BMI1 might be a potential therapeutic target for the elimination of tumor-initiating SP fractions in HCC." (PMID 32987767, 2020). "Through genetic lineage tracing approach, we found that a group of Moloney murine leukemia virus insertion site 1- (Bmi1-) expressing cell populations present in the invasive front of the esophageal epithelium, providing a continuous flow of tumor cells for ESCC." (PMID 32884573, 2020). "Finally, the in vivo test showed similar results, whereby the knockdown of the Bmi-1 gene led to the inhibition of tumor growth, metastasis and chemoresistance through miR-27a and miR-155." (PMID 32580736, 2020). "Moreover, BMI1 re-establishment in SOX9-silenced tumor cells restored cell viability and proliferation as well as decreased p21CIPin vitro and tumor growth in vivo." (PMID 31941916, 2020). "A similar reduction could be detected for Bmi1 and Etv1, the latter as one of the possible driving forces in tumor development in this particular tumor model." (PMID 32373532, 2020). "Additionally, we discovered that the expression levels of circDONSON and BMI1 were decreased, while miR-802 expression was increased in tumor masses derived from circDONSON-decrease HGC-27/DDP cells with or without DDP treatment." (PMID 32581651, 2020). "Similarly, BMI1 restoration also increased the tumor growth capacity of SOX9 knockdown Panc-1 cells." (PMID 31941916, 2020). "Interestingly, BMI1 restoration completely abrogated the reduction of tumor growth elicited by SOX9 knockdown." (PMID 31941916, 2020). "Similarly, senescence induction by SOX9 silencing was significantly mitigated (over 50% reduction) by BMI1 restoration in tumor cells." (PMID 31941916, 2020). "Therefore, the overexpression of BMI-1 in lung carcinoma indicates aggressive tumor progression and poor prognosis." (PMID 31861404, 2019). "Oct4, Nanog, Sox2 and Bmi-1 are upregulated in PCa tissue and tumor-initiating PCa cells." (PMID 31238903, 2019). "Thus, our findings indicate that Huaier n-butanol extract suppresses the proliferation and metastasis of GC cells via a c-Myc-Bmi1-mediated approach, providing a new perspective for our understanding of the anti-tumour effects of Huaier." (PMID 30679589, 2019). "We reported in our previous study that folate-targeted cationic liposomes could efficiently transport Bmi1 siRNA to tumor tissue and resulted in enhanced anti-tumor effect when DOX was co-delivered." (PMID 31366257, 2019). "Moreover, low CHD7 expression in the G4 meduloblastoma subtype, in combination with BMI1 overexpression, has recently been shown to contribute to tumor formation." (PMID 30850678, 2019). "UA and Bmi1 siRNA delivered by folate-targeted liposomes could be efficiently uptake by tumor cells in vitro." (PMID 31366257, 2019). "Bmi1 siRNA delivered by folate-targeted liposomes could down-regulate the expression of Bmi1 in KB cells and tumor tissues extracted from mice." (PMID 31366257, 2019). "On the contrary, Bmi1 was significantly higher in the group of tumour samples." (PMID 30255595, 2018). "BMI1 might alter extracellular matrix structure and angiogenesis of tumor cells through regulating Focal adhesion and PI3K/AKT pathways." (PMID 29685168, 2018). "Therefore, there was a converse correlation between miR-200c and BMI1 in which the miR-200c exerts its tumor suppressor role via BMI1 inhibition in CRC patients." (PMID 30579343, 2018). "The results imply that deguelin is a well‐tolerated compound at the dose of 3 mg/kg, and the inhibitory effect of deguelin on the xenograft tumour growth may partly depend on the suppression of Bmi1 and the induction of Noxa expression." (PMID 30255595, 2018).
tumor (continued). "It is unclear whether these Bmi1 positive cells represent infiltrating inflammatory cells or derive from epithelial CRC tumor cells." (PMID 30150766, 2018). "Importantly, our studies further demonstrate that targeting BMI1 by PTC209 significantly inhibits CRPC tumor growth, and combinational targeting of BMI1 and AR achieves better efficacy than single agents alone." (PMID 29402932, 2018). "BMI1 may accelerate tumor genesis and metastasis through dysregulating tumor ECM and blood vessel assemblies." (PMID 29685168, 2018). "Furthermore, the tumor promoting effect of circRNA-0008717 was abolished by miR-203 mimics or Bmi-1 silencing vector." (PMID 29854278, 2018). "BMI1 presence determines tumor growth rate, grading and phenotype." (PMID 30364119, 2018). "Moreover, circRNA-0008717 acts as a tumor oncogene through sponging miR-203 and thereby promoting the function of Bmi-1." (PMID 29854278, 2018). "Importantly, tumor-initiating MCL SP cells are reported to express significantly higher levels of BMI-1 than other cell fractions." (PMID 29983879, 2018). "Given that Bmi1+ cells were shown to contribute to the clonal expansion in the developing tumors, these data suggest that Bmi1 expression was upregulated during tumor development." (PMID 28176811, 2017). "BMI1 knockdown prevented the VEGFA‐mediated increase in tumor‐initiating cell abundance." (PMID 28179359, 2017). "Furthermore, we found tumor growth was reduced in mice bearing xenograft tumors after andrographolide treatment via activation of miR-218/Bmi1 axis." (PMID 27926533, 2017). "Interestingly, the let‐7i/ERK3 axis is tightly controlled by BMI1, an oncoprotein well known to be important for tumor growth and recurrence, as well as metastasis." (PMID 28079973, 2017). "In our previous study, we showed that BMI1 mRNA expression in primary NSCLC tumors is positively associated with BMI1 mRNA expression in peripheral whole blood of operable NSCLC patients, suggesting the potential of measuring BMI1 mRNA in whole blood as a surrogate marker of tumor progression." (PMID 28445986, 2017). "We also measured the volume of tumor xenografts and found that the forced expression of miR-128 significantly inhibited tumor growth in vivo, and overexpression of Bmi-1 could restore the tumor growth." (PMID 28424413, 2017). "Based on our data, we suggest the following mechanism of tumor progression in the small intestine: original tumors are polyclonal; then, a single Lgr5- or Bmi1-positive cell proliferates and replaces other cells by clonal competition, resulting in the formation of large-size monoclonal tumors." (PMID 28176811, 2017). "Our previous study has found that Bmi1 was aberrantly overexpressed in oral tongue cancer and it was potently inhibited by HDACi (inhibitors of histone deacetylases) chemicals, which in turn resulted in impaired tumor growth." (PMID 29200967, 2017). "Thus, this study not only extends our knowledge about the upregulation of this PcG protein but also verifies that Bmi-1 is an important and promising candidate tumor biomarker to predict the prognosis of pediatric patients with ALL." (PMID 28122538, 2017). "Furthermore, PEITC treatment induced expression of pro-apoptotic genes in tumor cells, which was partially reversed by overexpression of PcG member BMI-1, suggesting opposing roles for PEITC and PcG proteins in control of tumor progression." (PMID 28079155, 2017). "Importantly, in vivo PTC-209 administration significantly reduced tumor growth in a HNSCC xenograft model probably by Bmi1 inhibition and impaired cell proliferation." (PMID 29200967, 2017). "Interestingly, BMI-1 also targets the p16INK4a gene to regulate various events of tumor progression." (PMID 28861107, 2017). "Next, we examined Bmi-1 expression in tumor xenografts with immunohistochemistry." (PMID 28424413, 2017).
tumor (continued). "While short-term exposure to high concentrations of PEITC (6–12 μM for 48 h) was sufficient to reduce tumor cell expression of BMI-1, marked decreases in the expression of key PcG complex proteins SUZ12 and EZH2 were only observed after long-term treatment (2.5 μM PEITC for 6 weeks)." (PMID 28079155, 2017). "By reducing BMI1, with a BMI1 inhibitor, we can kill tumour cells in these models." (PMID 28275388, 2017). "Recent studies have shown that multiple microRNAs could repress translation of Bmi-1 and thus block proliferation and metastasis of tumor cells." (PMID 26717043, 2016). "Thus, We guessed that ZEB2 induced tumor stemness through modulating miR-200/BMI1/SOX2 signals in NPC." (PMID 27589832, 2016). "Bmi-1 is a transcriptional regulator that promotes tumor cell self-renewal and epithelial to mesenchymal transition and its upregulation is associated with tumor progression, AMPK is an intracellular fuel-sensing enzyme and plays important roles in tumor cell growth and progression." (PMID 26717043, 2016). "Although our data suggest that a delayed DNA methylation process is initiated upon Bmi1 overexpression, investigation of different stages of tumor development in vivo will be required to better understand the dynamics and mechanisms of de novo DNA methylation at the EphA7 locus." (PMID 27533460, 2016). "It's a novel finding that Bmi-1 involves in tumor angiogenesis, and what's the mechanism?" (PMID 27009837, 2016). "Thus, Bmi-1 is accepted as an oncogene that alters cell cycle, senescence, and apoptosis by promoting tumor cell self-renewal and epithelial to mesenchymal transition (EMT)." (PMID 26717043, 2016). "Future studies therefore have to clarify whether BMI-1 inhibition specifically targets tumour-propagating cells in MM as well." (PMID 26935956, 2016). "To investigate whether BMI-1 is crucial for pancreatic CSCs metastasis in vivo, we performed an in vivo tumor cells metastasis assay." (PMID 26840020, 2016). "Moreover, Phesse and co-workers have observed that partial suppression of JAK/STAT3 signaling in APC-mutant mice is sufficient to diminish tumor growth by reducing Bmi-1 dependent repression of p21 and p16." (PMID 27489351, 2016). "Interestingly, BMI-1 expression levels were high in holospheres and relatively high in the majority of tumor cells from the merospheres." (PMID 26742076, 2016). "In any case, slow increases in DNA methylation of BMI-1 target genes including EphA7might in turn make them more amenable to further silencing events, finally leading to a highly methylated state as found in tumor cells." (PMID 27533460, 2016). "Here, we analyzed whether elevated levels of the polycomb repressor complex 1 (PRC1) components Bmi1 and Ring1b and their catalyzed histone modification H2AK119ub in ADMs and tumor cells, are responsible for the mediation of acinar gene silencing." (PMID 26716510, 2016). "Our results showed that enforced expression of miR-128 inhibited the HNSCC cell proliferation and tumor xenograft growth by mediating the expression of BMI-1, BAG-2, BAX, H3f3b, and Paip2 mRNAs, suggesting that miR-128 might act as a tumor suppressor." (PMID 25764126, 2015). "The genes CCND1, CDC6 and Bmi-1, when overexpressed, promote the proliferation of tumor cells." (PMID 26317630, 2015). "Previous studies have shown that Akt-mediated phosphorylation in other contexts can directly or indirectly block the activity of negative regulators of transcription such as C/EBPα or the Polycomb group protein Bmi1 to promote cell proliferation or tumor growth." (PMID 26146542, 2015). "This study sought to determine if COX4 regulates BMI1 and modulates tumor cell proliferation." (PMID 25726526, 2015).